BRCA2 (BRCA2 DNA repair associated)
Diseases named in the same sentence as BRCA2 in open-access papers (continued):
Sharing a sentence is not in itself a finding about the gene and the disease.
breast cancer (continued). "However, in the subset of patients with a germline BRCA1 or BRCA2 mutation who participated in a Phase II study of olaparib monotherapy, no confirmed objective responses were observed in the eight patients with breast cancer." (PMID 24063698, 2013). "To determine whether common genetic variants modify breast cancer risk for BRCA2 mutation carriers, we previously conducted a GWAS of BRCA2 mutation carriers from the Consortium of Investigators of Modifiers of BRCA1/2 (CIMBA)." (PMID 23544012, 2013). "Reports about ASE of both BRCA1 and BRCA2 to be associated with increased breast cancer risk indicated that in some of the cases, ASE could be explained by mutations activating the nonsense mediated mRNA decay." (PMID 23383130, 2013). "The PARP inhibitor, AZD2281 (Olaparib) given to patients with BRCA1- and/or BRCA2-deficient advanced breast cancer (of which >50% were triple-negative) in a single arm study resulted in an overall response rate of 41% and progression free survival of about six months." (PMID 23717600, 2013). "However, a study on BRCA1 and BRCA2, two genes well-known to be involved in human breast cancer, showed associations of these genes with mammary tumours in English Springer Spaniels." (PMID 23574728, 2013). "Women who carry BRCA2 mutations have an increased risk of breast cancer that varies widely." (PMID 23544012, 2013). "The lifetime risk of breast cancer associated with carrying a BRCA2 mutation varies from 40 to 84%." (PMID 23544012, 2013). "In addition to breast cancer, BRCA2 mutations are also linked to other types of cancer, including ovarian, hepatocellular, pancreatic, prostate and gastric tumors." (PMID 23833673, 2013). "In addition to BRCA1 and BRCA2, other breast cancer susceptibility genes have also been extensively studied in Chinese." (PMID 23318652, 2013). "To determine whether the breast cancer association with rs9348512 was limited to BRCA2 mutation carriers, we compared results to those in the general population genotyped by BCAC and to BRCA1 mutation carriers in CIMBA." (PMID 23544012, 2013). "The imbalance of DSS1 over-expression associated with BRCA2 expression could affect breast cancer development." (PMID 24289229, 2013). "However, large population-based studies of breast cancer have demonstrated that at least some mutations in these genes are associated with breast cancer risks that are comparable to the average risk associated with BRCA2 mutations." (PMID 23448497, 2013). "Several array comparative genomic hybridization (aCGH) studies of breast tumors and breast cancer cell lines point to commonly observed gains and losses on regions of chromosome 8, 13 and 17 – regions known to contain breast cancer associated genes such as BRCA2, ERBB2 and MYC." (PMID 23382830, 2013). "The high DSS1 expression that potentially maintains high-level BRCA2 expression might cause or enhance breast cancer proliferation and/or drug resistance." (PMID 24289229, 2013). "Prevalence of BRCA1 or BRCA2 germ line mutations varies considerably among ethnic groups, and in some countries, founder mutations are responsible for a significant proportion of breast cancer cases." (PMID 23683081, 2013). "BRCA1 and BRCA2 variations found to affect kinase binding to these sites will be invaluable in the prioritization for further functional characterization and/or association studies in breast cancer." (PMID 23704879, 2013). "Additional variants that are specific modifiers of breast cancer risk in BRCA2 carriers may yet be discovered; their detection would require assembling larger samples of BRCA2 mutation carriers in the future." (PMID 23544012, 2013). "The prevalence of BRCA1 and BRCA2 mutations were reported in 2.5–3.1% for sporadic breast cancers, in 19.4–42.9% for familial breast cancer patients with two or more affected first- and second-degree relatives with breast or ovarian cancers, and in 9.6–18.3% for early onset breast cancers." (PMID 22382806, 2012).
breast cancer (continued). "The second breast cancer susceptibility gene, BRCA2, is localized on the long arm of chromosome 13." (PMID 23519070, 2012). "Deleterious germline mutations in BRCA2 are rare but confer a high risk of breast cancer." (PMID 22513257, 2012). "In a retrospective cohort study comprising 2,020 women with unilateral breast cancer from 978 families with a BRCA1 or BRCA2 mutation, we could show that contralateral breast cancer depends on the affected BRCA gene and age at onset of the first breast cancer." (PMID 23216834, 2012). "Relatives of families with BRCA1 mutations were significantly younger at first breast cancers than those from families with BRCA2 mutations (P < 0.001) and both were significantly younger than patients from BRCA1/2 negative families (P < 0.001 and P < 0.001, respectively)." (PMID 23216834, 2012). "We also evaluated whether rs2180341 was associated with breast cancer risk in BRCA1 or BRCA2 mutation carriers, by genotyping 5,381 mutation carriers from 11 studies in the Consortium of Investigators on Modifiers of BRCA1/2 (CIMBA)." (PMID 22768030, 2012). "It is important to acknowledge that apart from environmental factor such as betel quid being the prime focus of this study, genetic risk factors such as BRCA1 and BRCA2, lifestyle risk factors such as diet and reproductive risk factors also contribute to breast cancer." (PMID 22937096, 2012). "This higher rate of BRCA2 mutation carriers may well explain the lower rate of BRCA2 promoter hypermethylation in the male breast cancer group compared with female breast cancers." (PMID 22765268, 2012). "However, BRRSO in BRCA1 and BRCA2 mutations carriers has proven to be effective in reducing the rates of ovarian cancer as well as reducing the rates of breast cancer in the under 50 age group." (PMID 22187038, 2012). "Heterozygous mutations in FA genes have been associated previously with increased breast cancer risk, and, conversely, bi-allelic mutations in breast cancer-associated genes BRCA2, BRIP1, PALB2, and RAD51C have been identified in persons with FA or FA–like syndromes." (PMID 23028381, 2012). "Germline BRCA1 or BRCA2 mutations account for 20–30% of familial clustering of breast cancer." (PMID 23284877, 2012). "Also, we found some evidence of association between a high expression haplotype and lower risk of developing breast cancer among carriers of germline mutations in BRCA2." (PMID 22513257, 2012). "Similarly, the HRs for BRCA2 breast cancer risk exclude the ORs from the general population for SNPs rs2380205 at 10p15 and rs614367 at 11q13." (PMID 22348646, 2012). "Of 625 early onset patients, BRCA1 and BRCA2 mutations were detected in 35 (6.4%) of 550 patients without other risks, in 16 (30.2%) of 53 patients with bilateral breast cancer, in one (100%) patient who also had ovarian cancer, and in one (5.3%) of 19 patients with multiple organ cancers." (PMID 22382806, 2012). "The clinical role of BRCA1 and BRCA2 mutation testing for younger women with breast cancer is in rapid transition because of advances in gene sequencing technologies and accumulating evidence for the contribution of BRCA mutation status to acute management of early breast cancer." (PMID 22838957, 2012). "We found that SNP rs10995190 ZNF365 is associated with BRCA2 breast cancer risk." (PMID 22348646, 2012). "Canine BRCA2 missense mutations have also been reported in mammary tumors." (PMID 22471976, 2012). "For BRCA1 mutation carriers, only SNP rs10771399 at 12p11 was associated with the overall risk of breast cancer, whereas SNPs rs10995190 at 10q21, rs1011970 at 9p21, rs865686 at 9q31.2 and rs1292011 at 12q24 were associated with breast cancer risk for BRCA2 mutation carriers." (PMID 22348646, 2012). "The BRCA2 mutation was detected in one of the male breast cancer patients." (PMID 23519070, 2012). "The findings suggest that canine BRCA2 may be a good model for studying human breast cancer caused by analogous mutations." (PMID 23071527, 2012).
breast cancer (continued). "Therefore, likelihood of our samples containing BRCA1 mutations would still be minute if the probability of BRCA1 and BRCA2 mutations taken together is estimated to be 5%, equal to the proportion in total breast cancer incidence." (PMID 22937096, 2012). "While it has been reported that the risk of contralateral breast cancer in patients from BRCA1 or BRCA2 positive families is elevated, little is known about contralateral breast cancer risk in patients from high risk families that tested negative for BRCA1/2 mutations." (PMID 23216834, 2012). "BRCA1 and BRCA2 are the most prominent breast cancer susceptibility genes." (PMID 21835029, 2011). "Mutations in BRCA2 have been linked to breast cancer predisposition." (PMID 21789034, 2011). "Mutations in the main high penetrance genes BRCA1 and BRCA2 are mostly found in families with multiple breast cancer cases particularly with early onset and with ovarian cancer, and may also affect breast cancer survival among the mutation carriers." (PMID 22171747, 2011). "Indeed, mutations are found throughout the BRCA2 gene in breast cancer patients (BIC database) suggesting an involvement of all functional domains in maintaining genomic stability." (PMID 22194698, 2011). "We identified a deleterious BRCA1 or BRCA2 mutation in 4.7% of the women with breast cancer." (PMID 22085629, 2011). "In addition, an earlier study on breast cancer samples from carriers of different BRCA2 mutations showed retention of the BRCA2wt allele in some cases, providing support for our conclusion." (PMID 21958427, 2011). "The relative risk of breast cancer in men associated with BRCA2 mutations is high." (PMID 21949660, 2011). "BRCA1 and BRCA2 are the most well-known genes predisposing to breast cancer." (PMID 21980511, 2011). "BRCA1 and BRCA2 are the most well-known breast cancer susceptibility genes." (PMID 21980511, 2011). "The risk estimates from this study suggest that women carrying the pathogenic variant, ATM c.7271T > G, or truncating mutations demonstrate a significantly increased risk of breast cancer with a penetrance that appears similar to that conferred by germline mutations in BRCA2." (PMID 21787400, 2011). "There is a close relation between the BRCA2 gene mutation and male breast cancer." (PMID 21291532, 2011). "However, there remains a need to identify additional susceptibility genes as it has become increasingly evident that BRCA1/BRCA2 mutations cannot explain all cases of familial breast cancer." (PMID 21835029, 2011). "Similar patterns were observed for SNPs rs3803662 in TOX3/TNRC9 and rs4973768 in SLC4A7/NEK10 in which the associations were predominantly with ER-positive breast cancer for both BRCA1 and BRCA2 mutation carriers, in line with results from studies of breast cancer in the general population." (PMID 22053997, 2011). "We therefore postulate that the event of acquired defects in the BRCA1 gene could have the same effect in BRCA2 mutation carriers, as seen in sporadic breast cancers." (PMID 21958427, 2011). "Known risk breast cancer susceptibility alleles have been genotyped in a large series of female BRCA1 and BRCA2 mutation carriers assembled by the Consortium of Investigators of Modifiers of BRCA1/2 (CIMBA) to evaluate their associations with risk of breast cancer for mutation carriers." (PMID 22053997, 2011). "To determine whether the network of genetic changes identified in relation to the BRCA2 locus at 13q13.1 is specific for BRCA2 mutated breast cancers, we looked at our previously published data on sporadic breast cancers." (PMID 21958427, 2011). "Some of these changes have been characterized to provide a clear contribution to the development and/or progression of the cancer and include overexpression of HER2/neu in about 20% of breast cancer, and hereditary mutations in BRCA1 or BRCA2 in approximately 5% of breast cancers." (PMID 21541295, 2011).
breast cancer (continued). "Inherited mutations in the BRCA2 gene greatly increase the risk of developing breast cancer." (PMID 21958427, 2011). "Mutations in BRCA2 have been linked to an elevated risk of breast cancer in young women, which has been demonstrated to be due to the inheritance of dominant susceptibility genes conferring a high risk of breast cancer." (PMID 20953429, 2011). "Germ line mutations in BRCA1 and BRCA2 account for 5% to 10% of all breast cancer in women, and correspondingly in dogs, germ line mutations in the same genes, as determined by candidate gene association, have also been shown to predispose to canine mammary carcinoma." (PMID 24212780, 2011). "We successfully genotyped 24 SNPs in a cohort of up to 4,724 BRCA1 and 2,693 BRCA2 female mutation carriers from 15 study groups and assessed whether these variants were associated with risk of breast cancer in BRCA1 and BRCA2 mutation carriers." (PMID 21114847, 2010). "Whilst the risk of breast and ovarian cancer in the general population is 10%-13% and 1.7%, respectively, studies indicate that a woman with mutations in either BRCA1 or BRCA2 carries a lifetime breast cancer risk of 80% and 20%-60% for developing breast cancer and ovarian cancer respectively." (PMID 20961453, 2010). "Our results provide evidence for the existence of familial factors, such as variants in genes other than BRCA1 and BRCA2, which contribute to the increased risks for breast, prostate, lung and/or brain cancers in relatives of women with very early-onset breast cancer." (PMID 20877337, 2010). "To determine whether common genetic variants modify the penetrance of BRCA2 mutations, we conducted the first genome-wide association study of breast cancer among women with BRCA2 mutations using a two-stage approach." (PMID 21060860, 2010). "Indeed, the inheritance of a mutated form of the breast cancer susceptibility gene BRCA2 has been linked to the development of prostate cancer, although the precise role that BRCA2 dysfunction plays in the development of prostate cancer is unclear." (PMID 20585617, 2010). "In some settings, such as breast cancer associated with BRCA1 or BRCA2 mutations, allelic expression imbalance may underlie increased disease risk." (PMID 20470418, 2010). "Perhaps because the majority of BRCA2-associated breast tumors are estrogen receptor (ER)-positive, as are the majority of non-hereditary breast cancers, risk alleles for sporadic breast cancer are more likely to be modifiers of risk of BRCA2-associated hereditary breast cancer." (PMID 21060860, 2010). "An intriguing thought is the possibility that these genes may act as potential modifiers of BRCA1 and/or BRCA2 associated breast cancer risk." (PMID 20174566, 2010). "BRCA1 and BRCA2 genes mutations are responsible for a significant proportion of breast cancer." (PMID 20579331, 2010). "Furthermore, in BRCA1 or BRCA2 carriers with breast cancer, Tamoxifen use was associated with the prevention of secondary and contra lateral breast cancer." (PMID 20961453, 2010). "As previously noted, the stage 1 HRs among BRCA2 mutation carriers, reported here, were nearly identical to odds ratio estimates observed in sporadic breast cancer studies, consistent with a simple multiplicative interaction between the BRCA2 mutant alleles and the common susceptibility SNPs." (PMID 21060860, 2010). "The risk of breast cancer associated with BRCA2 mutations varies widely." (PMID 21060860, 2010). "Observed BRCA2 variants in breast cancer cases diagnosed before age 40 in the ABCFS." (PMID 20807450, 2010). "BRCA1 and BRCA2 genes have been identified that confer a high degree of breast cancer risk." (PMID 20579331, 2010). "Approximately half of all hereditary breast cancers are due to loss of BRCA1 or BRCA2 function." (PMID 20630075, 2010).
breast cancer (continued). "Although prophylactic mastectomy is the most effective intervention for BRCA1 and BRCA2 carriers, reducing the risk of developing breast cancer by 90%, mastectomy is a highly invasive procedure with adverse physical and potentially devastating psychological effects." (PMID 21037853, 2010). "This study describes a new human breast cancer xenograft obtained from a BRCA2-mutated patient." (PMID 20877358, 2010). "Most notable was the evidence that the SMAD3 gene, which encodes a key regulatory protein in the transforming growth factor beta signalling pathway, may contribute to increased risk of breast cancer in BRCA2 mutation carriers." (PMID 21114847, 2010). "In this GWAS of BRCA2 mutation carriers, the first in this high risk population, we found previously identified breast cancer susceptibility loci modified risk of BRCA2-associated breast cancer with similar magnitude of association." (PMID 21060860, 2010). "Mutations in BRCA1 and BRCA2 are found in a proportion of multiple case breast cancer families." (PMID 20807450, 2010). "Mutations in BRCA1 and BRCA2 confer high risks of breast cancer and ovarian cancer." (PMID 20482762, 2010). "Approximately half of hereditary breast cancers have mutations in either BRCA1 or BRCA2." (PMID 20614009, 2010). "The fact that the breast cancer occurred in a male proband who subsequently developed prostate cancer also raised the possibility of his having an unusual presentation of a BRCA2 mutation, as lifetime risk (to age 70) of these tumours is increased to about 7% and 20% respectively." (PMID 19493351, 2009). "Our results also imply that recommendation of full screening of the BRCA1 and BRCA2 genes, and even additional predisposing genes, to all breast cancer patients should remain the ultimate goal as new technologies emerge that can lower the cost and effort involved." (PMID 19491894, 2009). "Smoking may contribute to the familial aggregation of pancreatic and lung tumours, and the familial clustering of pancreatic and breast cancer could be partially explained by inherited mutations in the BRCA2 gene." (PMID 19826425, 2009). "Mutations in BRCA2 gene have been detected in up to 40% of male breast cancers in Iceland; in our isolated population, we detected a BRCA2 mutation in 1/14 (7%) men with breast cancer with a frequency similar to that reported for male breast cancers in USA (4%)." (PMID 19619314, 2009). "Slightly elevated risk of colon and prostate cancer in BRCA1 mutation carriers and increased risk of other malignancies including pancreatic, stomach and head and neck cancers and a large increase in the relative risk for male breast cancer is seen in BRCA2 mutation carriers." (PMID 19656415, 2009). "The availability of rapid genetic testing for BRCA1 and BRCA2 mutations has made it possible to follow unaffected carriers in greater numbers and to search for inherited mutations in women with a severe family history of breast cancer." (PMID 19718449, 2009). "In approximately 15% of the DNA mutation scannings of BRCA1 or BRCA2 in breast cancer families, the test result is difficult to interpret because an unclassified variant is found (UV, or 'variant of uncertain clinical significance' (VUCS) or 'variant of uncertain significance' (VUS)." (PMID 19563646, 2009). "Here we report the functional characterization of a novel de novo BRCA2 splice site mutation located in the intervening sequence (IVS) of exon 21 (nucleotide 8982+1 G→A/c.8754+1 G→A) in a Danish breast cancer patient with a family history of breast cancer." (PMID 18597679, 2008).